IL2 (interleukin 2)
Diseases named in the same sentence as IL2 in open-access papers (continued):
Sharing a sentence is not in itself a finding about the gene and the disease.
cancer (continued). "Of note, Interleukin-2 (IL-2) is one of the most well-studied and became the first immunotherapy that was approved by the US Food and Drug Administration (FDA) for cancer treatment nearly 30 years ago." (PMID 35806311, 2022). "A change in biomarkers like genotoxicity, labeling index, labeled cells/crypt, transepithelial resistance, necrosis, interleukin-2 (IL-2), IFN-γ prevents disease progression in cancer patients and in patients following polypectomy." (PMID 35910609, 2022). "A single COVID‐19 vaccine dose induced IFN‐γ and/or IL‐2 SARS‐CoV‐2‐specific T‐cell responses in 116 of 128 (90·6%) healthy donors, reducing significantly to 27 of 56 (48·2%) when measured in cancer patients (p < 0·0001)." (PMID 34775604, 2022). "The anti-viral or anti-cancer activity of CD8+ T cells is mediated by a polyfunctional Type1 cytokine response (e.g., IL-2, IFNγ, and TNFα)." (PMID 36619639, 2022). "Therefore, IL-7 might mitigate the side effects of using IL-2 in cancer immunotherapy." (PMID 36142322, 2022). "These genes were also active in pathways in cancer, immune signalling, cytokine signalling, signalling pathways like JAK/Stat, HIF-1, IFN-γ, IL-2, and PD-L1, among various others." (PMID 34685742, 2021). "Due to the enhanced immune activation as a result of targeted IL-2 delivery to T cells, AnnV-IL2 has relevant translational implications in the context of anti-cancer therapies." (PMID 34804041, 2021). "With 10 identifiers, we observed that these genes interacted with stemness genes such as SOX-2 and NANOG, genes important in cancer pathways such as STAT3, CTNNB1, EGFR, TNF, and CASP3, and immune genes such as IL2 and CD4." (PMID 34685742, 2021). "This variant is clinically interesting due to studies demonstrating that NR2F6-/- mice had enhanced IL-2 and IFN-gamma secretion, favoring T cell-mediated cancer cell elimination." (PMID 34589432, 2021). "The idea of conjugating PEG chains to IL-2 for extended circulating half-life originated in 1987, launching nearly a decade of research and clinical trials exploring PEG-IL2 for cancer immunotherapy." (PMID 34790830, 2021). "In patients with HCC, high level of IL‐2 further activated CD8+ cells, promoting them to secrete IFN‐γ to enhance the efficiency of killing cancer cells." (PMID 34605616, 2021). "Interleukin-2 (IL-2) and interferon α (IFN-α) are the first two cytokines approved for the treatment of cancers." (PMID 34579759, 2021). "Until now, three cytokines (i.e., IL-2, IFN-α, and granulocyte-macrophage colony-stimulating factor (GM-CSF)), have been approved by the FDA for the treatment of several cancer types." (PMID 33918635, 2021). "For example, interleukin 2 (IL-2) influences T-cell growth, expansion and cytotoxicity, and is approved by the FDA for the usage in cancer treatment." (PMID 34445701, 2021). "m6A-C2 cluster is distinguished by cancer and immune surveillance, involving epithelial mesenchymal transition, TGF-β signal, TNF-α signaling via NF-κB, and IL2/STAT5 signaling." (PMID 34993195, 2021). "Based on these data, we created c-Met CAR T cells from primary T cells, which showed high IL-2 and IFN-γ secretion when incubated with the c-Met positive cancer cell line." (PMID 34830894, 2021). "In contrast, DNA demethylation and high expression of IFNγ and IL2 genes occur in both Th1 and CD8 T cells, which results in a better anti-cancer immune response." (PMID 33535484, 2021). "Interleukin-2 induces CSRNP1 (also known as Axin1 upregulated 1; AXUD1) in mouse T cells; it expresses a 1.7 kb transcript with five exons in some malignant cancers, such as kidney, liver, lung, and colon carcinomas." (PMID 33869003, 2021). "MUC1, together with interleukin 2, was also used to develop TG4010, a cancer vaccine based on a viral vector, a Modified Vaccinia Virus Ankara, encoding for their genes." (PMID 34453261, 2021).
cancer (continued). "For instance, in vivo activation of NK cells using cytokine treatments (e.g., IL2, IL12, IL15, IL18 and IL21) has been investigated in several types of mouse cancer models and human cancers." (PMID 35008348, 2021). "Through the stimulation of IL-2, NK cells upregulate the expression of SIRPα, which interacts with the inhibitory ligand CD47 expressed on cancer cells, delivering an inhibitory signal to NK cells." (PMID 34439285, 2021). "As the cancer cells are destroyed by oncolysis, new viruses or virions are released along with cytokines (e.g. GM-CSF, IL-2, IFN-gamma, etc.)and tumor antigens that further stimulate the immune system activity against cancer." (PMID 33902630, 2021). "The Th1 immune response can be usually inhibited in a variety of malignant tumors, which manifests as the down-regulation of TNF-α, IL-2, IFN-γ and IL-2, and defecting the proliferation of cytotoxic T cells, macrophages and NK cells." (PMID 34722304, 2021). "For example, if a therapeutic aims to revive exhausted T cells, a 3D co-culture of cancer spheroids, CAFs, and immune cells could be developed and treated with compounds, and supernatants are assayed for cytokines indicative of immune activation, e.g., IL-2, IFNγ." (PMID 33564739, 2021). "TILs activated by the blocking of the PD-1/PD-L1 interaction release antitumor cytokines containing interleukin-2 (IL-2) and interferon (IFN)-γ, which indirectly help the immune system fight cancer cells." (PMID 34659228, 2021). "Even though these cancer immunotherapy approaches have been recently shadowed by the tremendous success of immune checkpoint inhibitors (ICI), IL-2 therapy is still being used to treat certain cancers such as renal cell carcinoma." (PMID 33671123, 2021). "In the context of NB, MSC-delivered chemotherapeutic agents (paclitaxel), soluble factors with an anti-cancer effect (TNF-related apoptosis-inducing ligand (TRAIL), IFN-β, IFN-γ, IL2), microRNAs (miR-124), and oncolytic viruses have been studied so far." (PMID 33668854, 2021). "To date, only interferon-α (IFN-α) and IL-2 have been approved by the Food and Drug Administration (FDA) for cancer treatment." (PMID 33803078, 2021). "By using the ELISA cytokine (Abcam) kit, results of CAR-T cells' ability to release cytokines IL-2 and IFNg showed that CAR-T cells were capable of releasing these cytokines when interacting with cancer cells A549." (PMID 34189144, 2021). "However, the mechanism of IL-2 in treating pediatric cancers remains unknown." (PMID 34872514, 2021). "The pivotal roles of IL-2 and IL-15 in activating CD8+T cells lead to the wide usage of these two cytokines in cancer immunotherapy." (PMID 33266177, 2020). "TG4010, a therapeutic cancer vaccine, expressing MUC1 as well as interleukin 2, and is combine with PD-L1 immune inhibitor nivolumab, has been approved by the FDA for the first-line treatment of patients with NSCLC." (PMID 33208183, 2020). "The Food and Drug Administration (FDA) has approved Interleukin 2 (IL-2) and Interferon-α (IFN-α) for cancer treatment." (PMID 33194364, 2020). "Signaling pathways most affected in hiPSC-CMs were related to cell cycle (i.e., pathways in cancer, PI3K-Akt signaling pathway), immune system (i.e., interleukin-2 signaling pathway, T-cell receptor regulation of apoptosis), hemostasis and platelet activation." (PMID 33233425, 2020). "In the early days of immunotherapy against cancer, some cytokines that regulate the Th1 response (IFN-γ, IL-2) were used together with nivolumab and ipilimumab." (PMID 33276556, 2020). "So, an approach that we propose to boost the anticancer response of the immune system is to “tag” cancer cells with specific antibodies, and activate both the antigen presentation and lymphocytes with Th1 cytokines (IFN-α, TNF-α, IL-2, IFN-γ, and IL-12)." (PMID 33276556, 2020). "Interleukin 2 (IL2) is one of the first cytokines which, along with interferon α (IFN-α), was used for the treatment of cancer." (PMID 32560387, 2020).
cancer (continued). "Accordingly, upon TM-mediated cancer cell lysis, UniCAR T-cells secreted the cytokines TNF-α, IFN-γ, GM-CSF and IL-2." (PMID 32370811, 2020). "Our results, along with the findings of other authors, indicate the ability of the CV extract to induce the production of many cytokines, including IL-1β, IL-2, IL-6, IL-10, TNF-α, and IFN-γ, by immune cells and cancer cells." (PMID 33260615, 2020). "For example, Oncoquest‐L, a cancer vaccine under phase II clinical trial (NCT02194751) is manufactured from an extract of patient's own cancer cells and IL‐2 delivered by proteoliposome." (PMID 31508270, 2019). "The remaining CD5-depleted cells were then exposed to human IL-2, IL-15, IL-2/IL-15 combination or the feeder cell line EL08-1D2, which is derived from murine embryonic liver cells, instead of human cancer cells, like the K562 line." (PMID 31717876, 2019). "Hematopoietic cytokines, such as granulocyte-macrophage colony-stimulating factor (GM-CSF), interleukin-2 (IL-2), erythropoietin (EPO), and thrombopoietin (TPO), are sometimes used to accelerate the hemopoietic recovery during cancer therapy." (PMID 32038252, 2019). "Although statistically not certain, due to a limited number of tested replicates, the increase of IL-2 induced p-STAT5 in I10 suggests cross-talk between T cells and cancer cells, through direct contact." (PMID 31409016, 2019). "NK cells cytotoxic effects against cancer cells is mediated by NKG2D and IFNγ upregulation and induction and are enhanced in the presence of IL2." (PMID 31457012, 2019). "Gene-set enrichment analysis of hallmarks of cancer pathways has shown that several important pathways are upregulated in response to SK1/SK2 KD, most notably KRAS, IL2/STAT5, EMT and TNF/NFκB (SK1 KD) and EMT, G2/M and E2F (SK2 KD)." (PMID 30971929, 2019). "Lymphocytes obtained from cancer patients by repeated leukapheresis were incubated with IL-2 to generate LAK cells, which were administered to the patients in conjunction with IL-2." (PMID 31614472, 2019). "Among those cytokines, IL-2 and IFN-γ are known as anti-tumor cytokines, which help to execute cancer cells and activate T and NK cells cytotoxicity." (PMID 31372176, 2019). "The first cytokine described to enhance NK cell activity was IL2 and, to date, is the only Food and Drug Administration (FDA) approved cytokine for the treatment of cancer patients." (PMID 31614774, 2019). "Tα1, as an immunomodulator used in cancer therapy, has abilities to induce the activation of DCs and T cells as well as the secretion of interferon-gamma (IFN-γ) and interleukin-2 (IL-2)." (PMID 30109250, 2018). "FSD13 had a greater ability than wild-type IL-2 in stimulating CD4+ T, CD8+ T, and NK cell proliferation, enhancing the expression of CD69, CD183, CD44, and CD54 in these cells, and triggering cancer cell apoptosis." (PMID 30250191, 2018). "Thus, starvation of cytokine, such as IL-2, may emerge as a new firearm among the arsenal of immunotherapeutic strategies, which either alone or in combination, enrich the picture of immune checkpoint inhibitors available to fight cancers." (PMID 29593717, 2018). "Here, the authors show that the use of liposomes to intravenously deliver surface-anchored IL-2 and anti-CD137 proteins enables anti-cancer immunity and reduces the toxic side effects." (PMID 29295974, 2018). "TH1 cells secrete IFN-γ, IL-2 and TNF-α and thereby activate the ‘cellular immunity’ pathway which is responsible for protection against viruses, cancer and intracellular pathogens." (PMID 30229370, 2018). "In order to focus on the combination therapy of the two drugs, we consider in the model only the following variables: cancer cells (C), dendritic cells (DCs), CD4+ and CD8+ T cells, GM-CSF, PD-1, PD-L1, PD-1-PD-L1 complex, and cytokines IL-12 and IL-2." (PMID 28542574, 2017).
cancer (continued). "The mathematical model is represented by a system of partial differential equations, based on the interactions among cancer cells, dendritic cells, CD4+ and CD8+ T cells, cytokines IL-12 and IL-2, GM-CSF, PD-1, PD-L1, PD-1-PD-L1 complex and anti-PD-1." (PMID 28542574, 2017). "Several pro-inflammatory cytokines, including interleukin-2 (IL2), tumor necrosis factor (TNF) and interferon-α (IFNα), have been approved for clinical use in certain types of cancer." (PMID 28574434, 2017). "The variables include dendritic and cancer cells, CD4+ and CD8+ T cells, IL-12 and IL-2, GM-CSF produced by the vaccine, and a T cell checkpoint inhibitor associated with PD-1." (PMID 28542574, 2017). "It was hypothesised that biological stressors trigger over-expression of IL-2 in brainstem neuronal centres, inducing a neurochemical cascade that results in disturbed homeostatic control of cardiorespiratory responses, and eventual death; however, populations were confined to non-cancer diagnoses." (PMID 28384249, 2017). "Whatever the case, the results warrant future studies exploring CD5 targeting to improve the efficacy of currently available immunotherapeutic approaches against cancer such as IL-10, TGF-β inhibitors or IL-2/anti-IL-2 mAb immunocomplexes." (PMID 29296231, 2017). "TG4010 is a cancer vaccine construct consisting of a recombinant, highly attenuated modified vaccinia Ankara (MVA) virus strain expressing both the human MUC1 and IL-2 genes (MVA-MUC1-IL-2)." (PMID 28116088, 2017). "IL-2/IL-2R signaling has contradictory immunomodulatory effects, since it not only facilitates proliferation of cytotoxic CD8 T cells that kill cancer cells, but also suppresses the immune response by promoting inhibitory CD4+ Treg cells." (PMID 28545581, 2017). "Regardless of clinicopathological characteristics, significant expression differences were observed, including 10 upregulated genes (CCL4/18, CXCL1/10/11, IFNγ, IL2/6/12A, VEGFA) and 1 downregulated gene (HLA-A) in lymphocytes from malignant ascites." (PMID 28620375, 2017). "The model includes dendritic and cancer cells, CD 4+ and CD 8+ T cells, MDSC cells, interleukins IL-12, IL-2, IL-6, IL-10 and TGF- β, PD-1 and PD-L1, and the two drugs: BRAF/MEK inhibitor (with concentration γB) and PD-1 inhibitor (with concentration γA)." (PMID 28724377, 2017). "According to the results, a statistically significant increase of IL-2, IL-10, TNF-α, IFN-γ, and IL-17 was observed in patients with cancer compared with the control group." (PMID 26905729, 2016). "Because IL-2 has the ability to potently stimulate CTL and NK cells, the dimeric BsAb is an attractive candidate for cancer immunotherapy." (PMID 26678395, 2015). "Of 11 markers previously affected, 7 markers significantly changed in the same manner: IL-1β, IL-1α, IFN-γ, MIP-2, IL-2, MIG, and IP-10, with cancer (CA2)." (PMID 26113869, 2015). "The role of the pro-inflammatory cytokines IL-2, IFN-γ and TNF in cancer is usually considered to be well-established." (PMID 26500775, 2015). "In the whole panel of cytokines, only IL-1β, IL-2, IL-6, TNF-α, IL-8, and MCP-1 were found to be modified in cancer patients after RT." (PMID 24800238, 2014). "It has been reported that the expression level of immunosuppressive cytokines, such as IL-10, was significantly higher than that of immunostimulatory cytokines, such as IL-2 and IFN-γ, in various cancer patients." (PMID 24358317, 2013). "For example, immunomodulatory cytokines, including interleukin (IL)-2, IL-12, or IL-21, would be effective adjuvants in the enhancement of impaired ADCC in patients with cancer." (PMID 20029417, 2010). "MESOR of cortisol, TRH, GH, IL-2 and CD16 was increased in cancer patients, whereas MESOR of TSH, IGF-1, CD8, CD8bright, TcRδ1 and δTcS1 was decreased in cancer patients." (PMID 20565977, 2010). "MESOR of cortisol, TRH, GH, IL-2 and CD16 was increased, whereas MESOR of TSH, IGF-1, CD8, CD8bright, TcRδ1 and δTcS1 was decreased in cancer patients." (PMID 20565977, 2010).
cancer (continued). "For example, immunomodulatory cytokines including IL-2, IL-12, or IL-21 would be effective adjuvants in the enhancement of impaired ADCC in patients with cancer." (PMID 20029417, 2010). "Conventional liposomes carrying cytokines such as IL-2 and IFN-gamma were tested for their efficacy to deliver cancer antigens but showed limited promise in breaking tolerance." (PMID 21318177, 2010). "As the cancer progressed at the tongue root, the percentage of CD3+CD4+ T lymphocytes and NK cells and the levels of IFN-γ and IL-2 decreased gradually, while the percentage of CD3+CD8+ T lymphocytes and the levels of IL-4 and IL-10 increased." (PMID 17338814, 2007). "Thus, L-NAME could be a valuable adjunct to IL-2-based cancer therapy." (PMID 8546905, 1996). "The synergistic effect of combining not‐α IL‐2 and not‐β IL‐2 as a superior anticancer agent in mouse models of various tumors offers a promising strategy for developing receptor‐biased IL‐2 therapies for cancer treatment." (PMID 40108893, 2025). "Our functional hydrogel, composed of GH-GMA loaded with IL-2 and VEGF-C encapsulating T-LEC spheroids, holds promise as a fundamental platform for cancer immunotherapy, such as immune checkpoint inhibitors, or for engineering platforms to modulate the suppressive TME." (PMID 39776798, 2025). "Cancer prevention properties of the effective extracts and their active compounds were evaluated by measuring the levels of tumor necrosis factor-alpha (TNF-α), interleukin-2 (IL-2), and nitric oxide (NO) using commercial kits." (PMID 40022126, 2025). "Although not currently in regular clinical use, IL-2 has historically been trialed as a cancer therapeutic as well as for use in immune fortification for patients with HIV infection." (PMID 40099965, 2025). "IL2, predominantly released by antigen-activated CD4 + T cells, is pivotal in cancer immunotherapy." (PMID 41246353, 2025). "Some immunopotentiators, like IL-2 and TLR agonists, are already licensed for human use or in clinical trials for cancer, others, like STING agonists and NLR agonists, are still under investigation, with ongoing research exploring their potential in combination therapies." (PMID 40837119, 2025). "IL-2 controls essential cytolytic effector and metabolic programs in CTL, is a key cytokine for CD8 T cell anti-viral immunity and is also used to produce cytotoxic T cells for anti-cancer immunotherapy." (PMID 40359130, 2025). "At the same time, an abundance of inflammatory cytokines and cytokine receptors in the common target may be engaged in the cancer pathway, including TNF, IL6, and IL2." (PMID 39492771, 2025). "However, it is important to note that NK92MI cells, a modified IL-2-independent NK92 cell line derived from an NK lymphoma patient, is indeed a human cancer cell line." (PMID 39841705, 2025). "Pathway enrichment analysis further demonstrated that MMP11(+) F01 cells exhibited activation of pro-tumorigenic and immunosuppressive pathways (IL-2, angiogenesis, PI3K-AKT-mTOR, and TGFβ), while MMP11(−) F01 cells enriched anti-cancer and immunostimulatory pathways (IFN-α/γ)." (PMID 40607407, 2025). "The study illustrated the pleiotropic role of IL-2, with no expression in early stages of cancer, varying according to “stage worsening”." (PMID 40869161, 2025). "Despite early research dating back to 1996 that reported increased IL-2levels in the cerebrospinal fluid of adolescent PD patients, effective therapiestargeting IL-2 have not yet been developed, unlike the extensive research on IL-2in cancer treatment." (PMID 39801407, 2025). "However, these are estrogen-dependent cancers, which hormone has the opposite effect of TAC by increasing IL-2 levels and can raise TAC blood levels." (PMID 40647460, 2025). "It quickly became evident that new biotechnological tools were needed for the clinical application of IL-2 to overcome important negative factors in cancer therapy." (PMID 39852848, 2025).